MMP9 (matrix metallopeptidase 9)
Diseases named in the same sentence as MMP9 in open-access papers (continued):
Sharing a sentence is not in itself a finding about the gene and the disease.
glioma (continued). "L-NAME, an inhibitor of iNOS, inhibited MMP-9-/uPAR-induced glioma cell migration and invasion." (PMID 24325546, 2013). "Recently, it was demonstrated that the cochaperone stress inducible protein-1 (STI1), a cellular prion protein (PrPc) ligand, released by primary microglia cells promotes proliferation and migration of glioma cell lines in a PrPc-independent fashion (possibly involving MMP-9)." (PMID 23864876, 2013). "Similarly, a significant inhibition of the invasion potential of the control or MMP-9/uPAR-overexpressed glioma cells was noticed after L-NAME treatment." (PMID 24325546, 2013). "Furthermore, MMP-9, an endopeptidase that digests basement membrane type IV collagen, is induced by p-Erk in glioma cells." (PMID 23451269, 2013). "In human glioma cells, MMP-9 and uPAR have been found to be overexpressed." (PMID 24325546, 2013). "MMP-9/uPAR overexpression enhanced the potential of glioma cell migration and invasion." (PMID 24325546, 2013). "MMP-9 and/or uPAR knockdown by respective shRNAs reduced iNOS expression in these glioma cells." (PMID 24325546, 2013). "Moreover, this invasion was suggested to be promoted by an increase of MMP-9 (matrix metalloprotease 9) expression in the CD133+ glioma cells." (PMID 23864876, 2013). "A key mechanism in the expansion and invasion of gliomas is the degradation of extracellular matrix by membrane-bound or secreted proteases such as MMPs, especially matrix-metalloproteinase-2 and MMP-9." (PMID 24023566, 2013). "MMP2 and MMP9 protein expression levels are key indicators of glioma cell invasion." (PMID 23251243, 2013). "Although few normal cell types express MMP-9 under normal physiological conditions, the majority of human metastatic tumor cells that have been tested consistently show elevated MMP-9 activity compared with benign control cells, including melanoma, fibrosarcoma, breast adenocarcinoma, and glioma." (PMID 23407024, 2013). "Bmi-1 may play an important role in the development of aggressive phenotype of glioma via activating the NF-kappaB/MMP-9 pathway and therefore might represent a novel therapeutic target for glioma." (PMID 22967049, 2012). "Furthermore, expression of Bmi-1 correlated with NF-kappaB nuclear translocation as well as MMP-9 expression in clinical glioma samples." (PMID 22967049, 2012). "Our current study indicates that Bmi-1 modulates the NF-kappaB/MMP-9 signaling pathway to mediate an aggressive phenotype in human glioma, suggesting that Bmi-1 may represent a potential therapeutic target for the treatment of glioma." (PMID 22967049, 2012). "Additionally, it exhibited inhibitory effects on inducible nitric oxide synthase (iNOS) protein expression and MMP-9 enzyme activity in glioma cells." (PMID 22272328, 2012). "Furthermore, the overexpression of miR-211 significantly suppressed MMP-9 activity in glioma cells, as demonstrated by gelatin zymography." (PMID 23183822, 2012). "In particular, MMP-2 and MMP-9 are the two most abundant MMPs found in gliomas." (PMID 20587068, 2010). "Therefore, it has been proposed that MMP-2 and MMP-9 inhibitors can act as potential drugs for the treatment of gliomas." (PMID 20587068, 2010). "To determine whether doxycycline can block MMP activity, we measured the extent of doxycyline-mediated MMP-2 and MMP-9 inhibition in vitro using epidermal growth factor receptor (EGFR) transfected U251 glioma cell lines." (PMID 18186943, 2008). "Doxycycline can block MMP-2 and MMP-9 activities from glioma cells in vitro." (PMID 18186943, 2008). "In this study we determined whether or not doxycycline could block MMP-2 and MMP-9 activities, by measurements of doxycyline-mediated MMP-2 and MMP-9 inhibition in vitro using epidermal growth factor receptor (EGFR) transfected U251 glioma cell lines." (PMID 18186943, 2008).
glioma (continued). "Immunohistochemical analyses of pioglitazone-treatedanimals revealed that protein levels of MMP-9 (matrix metalloproteinase 9), which has shown to be intimatelyinvolved in glioma migration and invasion, were substantially reduced in the bulk tumorand the tumor margins." (PMID 18815619, 2008). "Similarly, the serum MMP-9 levels, assessed via ELISA, were found to increase in patients with high-grade gliomas following tumor resection, likely reflecting heightened inflammation triggered by surgery, as MMP-9 is known to rise during inflammatory processes." (PMID 40265458, 2025). "Furthermore, investigations into the regulatory mechanisms governed by Snail have unveiled its ability to modulate the expression of critical EMT-associated molecules such as E-cadherin, Notch1, vimentin, and MMP-9 in various cancer cell types, including gliomas." (PMID 40575155, 2025). "However, 1 healthy subject and 73 glioma patients showed higher MMP-9 levels than the threshold." (PMID 40512281, 2025). "Moreover, our study revealed that the expression levels of four genes (POSTN, CHI3L1, SAA1, and MMP9) were significantly elevated in glioma samples obtained from patients who experienced recurrence within one year after TMZ treatment, along with an increased risk score." (PMID 39574472, 2024). "Thus, more effeorts should be directed towards investigating whether AQP4 redistribution impacts MMP-9-related malignancy in glioma patients." (PMID 39247976, 2024). "However, exploring the precise mechanisms regarding the interaction between AQP4 and MMP-9 could be of great significance for revealing the roles of AQP4 redistribution in glioma progression and treatment." (PMID 39247976, 2024). "In addition, L1 overexpression significantly induces the upregulation of MMP2 and MMP9 expression in U87, T98, and GBM1 cells, suggesting that L1 might promote tumor invasion through upregulating MMP2 and MMP9 in glioma cells." (PMID 36708044, 2023). "Given that MMP9 has been proposed as a prognostic and diagnostic marker in glioma, our observations that MUC4 was at least as efficient as MMP9 in discrimination between grades indicates it may act as a biomarker in glioma diagnosis." (PMID 36400876, 2022). "PI3k/Akt signaling regulates angiogenesis by affecting expressions of VEGF, HIF-1α, and MMP9.Activation of PI3k by Notch1 also stimulates the signaling pathways of MMP9, β-catenin, and NF-κB, which increases the migratory, invasiveness, and angiogenic properties of glioma cells." (PMID 36643842, 2021). "Moreover, EN2 blocks the invasion of glioma cells by inhibiting MMP9 expression." (PMID 32158355, 2020). "Moreover, downregulating SCD1 could decrease the expression of PCNA and MMP-9; thus, the proliferation and invasion of glioma cells were weakened." (PMID 33585189, 2020). "Finally, functional analysis showed that PLD1 overexpression could facilitate the propagation of glioma cells in a manner dependent on CyclinD1 as well as CKD4, and promote the migration of glioma by upregulating MMP9 secretion." (PMID 28915652, 2017). "Our results showed that MMP-9 (92 and 240 kDa) is significantly increased in the sera from patients with CNS tumors compared to healthy individuals and differences in MMP-9 tissue expression have been underlined between glioblastoma and low-grade glioma specimens." (PMID 27757720, 2017). "Thus, MMP-9 expression is likely to be one of several complex mechanisms that may impact the glioma immune microenvironment." (PMID 28591697, 2017). "al. demonstrated that MMP9 is predominantly expressed by glioma-associated microglia/macrophages in mouse and human glioma tissue not by glioma cells, and glioma-associated microglial MMP9 expression is upregulated by TLR2 signaling and is sensitive to minocycline." (PMID 27022952, 2016). "In addition, MMP-9 appears to be involved in the invasion and metastasis of glioma tumors." (PMID 26663949, 2015).
glioma (continued). "Recent studies confirmed that IDH1 mutation is associated with better prognosis in patients with glioma by inducing cell cycle arrest in G1 phase, inhibiting cell proliferation, and reducing invasion ability, by reducing the levels of matrix metalloproteinases MMP2 and MMP9." (PMID 25695077, 2015). "HMGB1 was found to up-regulate the expression of MMP-9, which belongs to matrix metalloproteinases (MMPs) involved in the initiation, invasion, and metastasis of many kinds of cancers, in glioma and gastric cancer cells, which may explain its association with invasion and metastasis of glioma tumor." (PMID 25772485, 2015). "Furthermore, MMP-9 and IL-8 expression are further increased in Bmi-1-overexpressing glioma cells." (PMID 23383216, 2013). "MMP-9 expression could be correlated with high malignancy and progression of gliomas." (PMID 24023566, 2013). "Moreover, the invasivenes of Bmi-1-overexpressing glioma cells could be abrogated by an MMP-9 inhibitor, suggesting that MMP-9 played an important role in mediating Bmi-1-induced invasion of glioma cells." (PMID 22967049, 2012). "Given the insensitivity of some GBMs to radio- and chemotherapy (temozolomide) and the hypothesis that glioma stem cells cause resistance to drug therapy, we investigated whether miR-211 endows radiosensitivity to glioma cancer stem cells by synergistic downregulation of MMP-9." (PMID 23183822, 2012). "In the present study, we demonstrated that either the downregulation of MMP-9 (pM) or overexpression of miR-211 increases chemo- and radio-sensitivity of glioma CSC, suggesting that rescuing miR-211 expression may have a new therapeutic application in the treatment of GBM patients in the future." (PMID 23183822, 2012). "SB4 and SB5 suppressed the spheroid formation of lung cancer (H1975) cell line, glioma (U87) cell line, and gastric cancer (AGS) cell line and, SB4 and SB5 suppressed the MMP9 protein level in the AGS." (PMID 41179704, 2025). "Evidence from prior studies show that FN1 enhances glioma development by interacting with integrin b, and activating MMP2/MMP9 to accelerate the invasion and metastasis of cancer cells." (PMID 41199745, 2025). "This study discovered that metabolites derived from gut microbiota can suppress cell migration in glioma cells by reducing the expression of MMP2 and MMP9." (PMID 40873641, 2025). "This study demonstrates that Calanquinone A effectively inhibits glioma cell proliferation and migration by targeting the STAT3/c-Myc and MMP9 signaling pathways." (PMID 40759869, 2025). "P2X7R inhibition has also been reported to downregulate MMP-9 expression in macrophages, whereas P2X7R stimulation enhanced PCNA expression in gliomas." (PMID 41034696, 2025). "Gene therapy has emerged as a novel strategy to modulate MMPs’ expression in gliomas, particularly by using gene silencing techniques such as RNA interference (RNAi) to knock down MMP-2 or MMP-9 expression." (PMID 40265458, 2025). "IL-4, IL-8, MMP-9 and PCNA promote glioma survival by inducing TAM immunosuppression, angiogenesis, glioma cell proliferation and clonogenic potential, and DNA replication and repair, respectively." (PMID 41034696, 2025). "Further analysis confirmed that the vesicles’ anticancer potential was mediated through inhibition of glioma growth via the PI3K/AKT pathway and suppression of cancer spread through decreased expression of matrix metalloproteinase 9 (MMP9)." (PMID 40648712, 2025). "Research has shown that Sch B can inhibit the migration and invasion of glioma cells by suppressing the expression of p-Akt, p-mTOR, and MMP-9 in the PI3K/Akt-mTOR-MMP-9 signaling pathway." (PMID 39995410, 2025). "Calanquinone A inhibits glioma cell proliferation and migration by targeting the STAT3/c-Myc and STAT3/MMP9 signaling pathways." (PMID 40759869, 2025). "Glioma cells are well known for their invasive potential, which is largely driven by matrix metalloproteinases (MMPs) such as MMP-2 and MMP-9." (PMID 41154863, 2025).
glioma (continued). "Collectively, these results demonstrate that Calanquinone A suppresses glioma proliferation and migration by targeting the STAT3/c-Myc and MMP9 pathways." (PMID 40759869, 2025). "So far, in gliomas, increased expression of MMP-2 and MMP-9 has been described, correlating with the degree of tumor malignancy." (PMID 39352533, 2025). "And by modulating the polarity of AQP4, MMP-9 inhibition could facilitate the glymphatic clearance of cytokines, as well as the draining of macromolecules and traffic immunological cells from the CNS into cervical lymph nodes, being a candidate curing strategy against glioma." (PMID 39247976, 2024). "There was no significant change in the expression of E-cadherin, however, the expression of N-cadherin, MMP-2, and MMP-9 decreased, further indicating that the downregulation of TBC1D1 affected the MMP family and thus weakened the aggressiveness of gliomas." (PMID 38189823, 2024). "Glioma cells can enhance their expression of CD44, the primary surface receptor for HA, which also binds to matrix metalloproteinase 9 (MMP9) present in the ECM." (PMID 39033204, 2024). "SRC‐1 directly binds to PEA3 and the VEGF and MMP‐9 promoters under VEGF and VEGF inducer GS4012 treatment in glioma cells." (PMID 38506084, 2024). "In comparison to other glioma subtypes, the GS2 exhibited higher expression levels of IBSP, PLA2G2A, NNMT, CA9, and MMP9, while the GS5 showed higher expression levels of CHI3L1, IGFBP2, EMILIN3, MEOX2, and PDPN." (PMID 38332637, 2024). "Glial Tumors Group: Notably, E-Selectin, ICAM-1, PAI-1, MMP-9, and eNOS were expressed predominantly, whereas VCAM-1 showed lower expression, and P-Selectin was not expressed." (PMID 38306519, 2024). "Levels of pro-apoptotic proteins (including Bad and cleaved-caspase-9) were increased, while the expressions of anti-apoptotic markers(e.g., MMP-9, MMP-2, and Bcl-2) were decreased in PQR309-treated glioma models." (PMID 38555280, 2024). "MMP-9 expression was significantly higher in grade IV gliomas (glioblastomas) compared to grade II and III gliomas." (PMID 39684754, 2024). "MMP7 and MMP9 are related to ECM remodeling and transcripts of both MMPs are up-regulated in high grade gliomas." (PMID 38272115, 2024). "Moving forward, it remains to be studied in other types of human cancers, given that the JICD1-TWIST1-MMP2 and MMP9 axes correlate with GBM aggressiveness, and nuclear-localizing JAG1 is observed in glioma patients." (PMID 38092725, 2023). "This is accompanied by an upregulation of its TLR1 and TLR2 expression and mediates an increase in MMP-9/MMP-14 expression, promoting microglia-mediated glioma progression." (PMID 37700840, 2023). "Cripto-1 is an oncogenic molecule that promotes the invasion of glioma cells and enhances the expression levels of MMP2 and MMP9." (PMID 37509289, 2023). "By decreasing cell growth and enhancing cellular proliferation, vanillin at a dose of 100 μM can decrease TLR2 expression and increase the expression of MMP‐9, MMP‐14, IL‐6, and iNOS expression in the glioma cell line GL261 at a dose dependent." (PMID 37675821, 2023). "For instance, TLR9, MMP-2, MMP-9, and MMP-13 expression is upregulated, while TIMP-3 is downregulated under hypoxic conditions (1% oxygen for 24 h) in glioma U373MG and D54MG cells." (PMID 38069210, 2023). "Similar to MMP-9, MMP-2 expression correlates directly with tumor grade and indirectly with survival in glioma." (PMID 37370851, 2023). "Subsequently, we explored the effects of DKK1 knockdown and found that it attenuated the vasculogenic networks in glioma cells and decreased the expression levels of metalloproteinases MMP2 and MMP9 and VE-Cadherin." (PMID 37906341, 2023). "By suppressing the expression of SLP2 by inhibiting the nuclear factor κB/matrix metalloproteinase-9 (NF-κB/MMP9) pathway, the migration ability of glioma cells can be reduced substantially." (PMID 37111654, 2023).
glioma (continued). "Quantitative PCR and immunohistochemical analysis showed that LIF, LOX, MMP9, S100A4, SRPX2, and TIMP1 were expressed at high levels in glioma, whereas SLITI1 and SMOC1 were expressed at low levels, consistent with our previous results." (PMID 36560848, 2023). "ROBO1 knockdown inhibited glioma invasive, migratory, and VM-formation abilities by suppressing the expression of matrix metallopeptidase 2 (MMP2) and matrix metallopeptidase 9 (MMP9)." (PMID 37238655, 2023). "It is possible to imagine that myeloid-derived MMP9 is accumulating in the TME and reaches a certain threshold necessary to promote glioma infiltration." (PMID 35992852, 2022). "Interesting, through multivariate COX regression analysis, we found that HOXC6, MMP9, SHOX2 and MYOD1 can act as independent prognostic factors for glioma." (PMID 36118887, 2022). "EGFR, MMP9, and MUC4 expression levels were assessed in FFPE tissue biopsies from 60 glioma patients (20 grade II, 20 grade III, and 20 GBM patients, following the 2016 WHO classification)." (PMID 36400876, 2022). "SERPINE2 is a protein that is secreted into the extracellular matrix, and it inhibits cell invasion in PCa and glioma, which is related to the inhibition of uPA, MMP-2, and MMP-9 activities." (PMID 36142828, 2022). "Heatmap analysis showed that WT1, HOXA2, HOXC6, MMP9 and SHOX2 are highly expressed in high-hypoxia glioma tissues in the TCGA, whereas MYOD1 expression is reduced." (PMID 36118887, 2022). "Mesenchymal markers, including N-cadherin, slug, snail and metastasis-related genes including MMP2, MMP9 and TIMP3 were widely investigated and verified in glioma remedy mechanisms." (PMID 36234681, 2022). "In conclusion, a risk model constructed by 6 hypoxia-driven genes (WT1, HOXA2, HOXC6, MMP9, SHOX2 and MYOD1) provide valuable clinical utility for the prognostic prediction of glioma patients." (PMID 36118887, 2022). "We first determined the expression HOXC6, MMP9, SHOX2 and MYOD1 in glioma tissues with promoter-methylation and promoter-unmethylation of MGMT." (PMID 36118887, 2022). "Curzerene, as a traditional Chinese medicine extract, can inhibit the malignant progression of glioma by downregulating GSTA4, p‐mTOR, MMP9, and other signals." (PMID 35048517, 2022). "Genes common to the top 5 activated pathways include POSTN, MMP9, CEBPB, CEBPD, and IGFBP5, which reportedly participate in glioma growth, invasion, and immunosuppression." (PMID 35814469, 2022). "Immunohistochemical staining also demonstrated that MMP9 and SPHK1 levels were apparently reduced, but LASS2 and TIMP2 levels were increased in glioma xenografts derived from U-87 MG-pLV-LASS2 cells compared with those derived from U-87 MG-pLV cells." (PMID 35517425, 2022). "In high grade gliomas, TAZ binds TEAD4 and modulates the expression of cyclin D1, Bcl-2 and MMP-9 (Matrix metallopeptidase 9), leading to cell proliferation and migration." (PMID 35602596, 2022). "The result indicated that overexpressed CBX7 and downregulated CBX8 in glioma cells showed a decreased expression of MMP2 and MMP9 and displayed significantly lower invasion abilities in scratch wound-healing assay when compared to the control." (PMID 36034290, 2022). "We further investigated the potential use of MMP9 and MUC4 proteins as serum biomarkers in glioma patients." (PMID 36400876, 2022). "Meanwhile, the glioma patients with higher PTBP1, SLC39A1, MMP9, and SLC16A3 expression had shorter OS (p < 0.01)." (PMID 36307882, 2022). "Immunohistochemistry (IHC) and immunofluorescence (IF) in fixed tissue samples of glioma patients were used to evaluate the expression and localization of EGFR, MMP9, and MUC4." (PMID 36400876, 2022). "The GL261 glioma cell line and activation of TLR2 upregulated the expression of MMP2 and MMP9 to promote tumor invasion, indicating that TLR2 signaling in glioblastoma stem cells (GSCs) is involved in the invasiveness of glioma." (PMID 36611945, 2022).